BCL3 (BCL3 transcription coactivator)
Diseases named in the same sentence as BCL3 in open-access papers (continued):
Sharing a sentence is not in itself a finding about the gene and the disease.
breast carcinoma (continued). "Moreover, abnormal expression of BCL3 was associated with prognosis in patients with CLL, breast cancer, clear-cell renal-cell carcinoma and non-small-cell lung cancer." (PMID 30357752, 2019). "Also, some reports suggested that Bcl-3 overexpression provides resistance against apoptosis following DNA-damage in a transformed breast cancer cell line ex vivo." (PMID 28915576, 2017). "Next, we detected the Bcl-3 expression ofdifferent breast cancer cell lines." (PMID 27906182, 2016). "Furthermore, BCL3 has been suggested to be involved in the pathogenesis of solid tumors such as nasopharyngeal carcinoma and breast cancer." (PMID 26219963, 2015). "In addition, estrogen withdrawal in breast cancer cell lines increased the expression and activity of Bcl-3, providing an alternative proliferation pathway and further advantage for tumor growth in mice." (PMID 22195643, 2011). "In this regard, it is interesting that, in addition to the known deregulation in leukemias and lymphomas, genome-wide expression studies have shown that Bcl-3 is overexpressed in breast cancer, glioblastoma tumors, ovarian cancer and, intriguingly, teratomas and embryonal carcinomas." (PMID 22195643, 2011). "More recently, a new interaction partner of Bcl-3, CtBP1, was found in breast cancer cells." (PMID 22195643, 2011). "Breast cancer was the first solid tumor in which evidence for Bcl-3 deregulation was found." (PMID 22195643, 2011). "In addition to this, Bcl-3 has been found to be deregulated in breast cancer, nasopharyngeal carcinoma, endometrial cancer and colorectal cancer." (PMID 22195643, 2011). "Since the initial discovery of Bcl-3’s involvement in hematological malignancies, subsequent research has revealed its dysregulation in various other cancer types, including colorectal cancer, ovarian cancer, breast cancer, cylindromatosis, skin cancer, liver cancer, and prostate cancer." (PMID 39327470, 2024). "BCL3-IRS might therefore become a valuable predictive biomarker for breast cancer." (PMID 35020071, 2022). "Indeed, we found that Bcl-3 depletion insome breast cancer cell lines, such as MDA-MD-231 and 4T1 cells, led tomesenchymal-to-epithelial transition (MET) induction, there was as demonstratedby reduced F-actin polarity and an obvious morph-change from fibroblast-like toround-like." (PMID 27906182, 2016). "Notably, Smad3 overexpression only partially rescued the deficiency caused byBcl-3 loss, suggesting that other mechanisms might be involved in the regulationof the pulmonary metastasis of breast cancer by Bcl-3." (PMID 27906182, 2016). "Hence, Bcl-3 may protect ERα-positive breast cancer cells, such as MCF-7 cells, against fulvestrant." (PMID 26515727, 2015). "Thus, by upregulating Bcl-3 levels in ERα-positive breast cancer cells, MSCs and CAFs may pave the way towards an NFκB-dependent growth under conditions where ERα is not functional." (PMID 26515727, 2015). "Interestingly, expression of Bcl-3 and CtBP1 is strongly correlated in breast cancer samples." (PMID 22195643, 2011). "DEGs Bcl3, ADGRG7, FABP4, IRF4, their regulating miRNAs and TFs have strong impact on proliferation and metastasis of breast cancer in bone tissues." (PMID 35388653, 2022). "We also investigated the role of Bcl-3 in the response to TNF stimulation in other cell types, including colon cancer cells and breast cancer cells." (PMID 34853447, 2022).
breast carcinoma (continued). "To assess the role of Bcl-3 in tumorigenesis, we utilized the MPA/DMBA carcinogen-induced mouse mammary tumor model to generate stochastic tumors." (PMID 35681213, 2022). "In breast cancer models it has been demonstrated that BCL-3 drives metastasis of tumour cells: In HER2-positive breast tumour cells, BCL-3 knockout (KO) resulted in an 80% reduction of metastatic burden in mice following tail-vein injection of tumour cells." (PMID 31930327, 2020). "For example, independent breast cancer studies have shown that AKT1 suppresses migration and metastasis and BCL3 inhibits apoptosis and tumor progression." (PMID 33371906, 2020). "Because BCL3 stimulates cell-cycle progression in a breast cancer cell line, and cell-cycle enhancement stimulates EGC formation, BCL3 likely enhances PGC reprogramming via cell-cycle control." (PMID 30286177, 2018). "Consistent results wereobtained in Bcl-3-depleted LM2, MCF-7 cells and the mouse breast cancer cellline 4T1." (PMID 27906182, 2016). "Interestingly, Bcl3 played a protective role against TNF/CHX-induced apoptosis in colon cancer cells and breast cancer cells." (PMID 40015625, 2025). "Accordingly, we selected the Bcl3 promoter as our experimental model among the 14 SP1-enriched, G4-containing candidates, based on its high G4-forming potential (G-score = 42; ranked 3rd) and its established relevance to breast cancer." (PMID 40884402, 2025). "Here, we set out to determine the role of Bcl3 in the maintenance of breast cancer cell survival in the absence of chemotherapeutic challenge." (PMID 38255248, 2024). "Bioinformatics analysis of in silico publicly available TNBC data identified BCL3 and BCL2 as well as the following anti-tumour immune response biomarkers as significantly altered in TNBC compared to other breast cancer subtypes: GZMA, PRF1, CXCL1, CCL2, CCL4, and CCL5." (PMID 38022682, 2023). "Bcl-3 has been reported to be instrumental in promoting mammary tumor metastasis in two mouse models of breast cancer; however, the role of Bcl-3 in normal mammary gland development and function has not been characterized." (PMID 35681213, 2022). "Disregulation of BCL3 without chromosomal translocation has been found to participate in progression in a variety of solid tumors, from breast cancer, nasopharyngeal carcinoma and renal-cell carcinoma to lung cancer." (PMID 30357752, 2019). "As p16 is frequently deleted in breast cancer cell lines and not expressed in MCF-7, ZR751 or T47D cells, we sought to determine whether or not a loss of Bcl3 resulted in alterations to p15 and p21 using qRT-PCR." (PMID 38255248, 2024). "Despite Bcl3’s well-recognised association with metastatic disease, recently attributed to its ubiquitous role in cancer cell migration, there is little evidence directly linking Bcl3 with the NF-κB mediated regulation of basal survival mechanisms in breast cancer." (PMID 38255248, 2024). "To assess whether the absence of Bcl-3 altered Bcl-2 expression in mammary tumors as it did during involution, we performed immunoblot for Bcl-2 in different tumor subtypes from bcl-3−/− and control mice." (PMID 35681213, 2022).
breast carcinoma (continued). "On the other hand, the failure of T47D cells to react this way upon exposure to stromal cells indicates that breast cancer cells do not necessarily respond to stromal cells by inducing changes in IGFBP5 and Bcl-3 expression." (PMID 26515727, 2015). "To confirm this result, we performed immunofluorescence staining and confocal microscopy of Bcl-3 localization in CACO-2, HCT-116, and breast cancer cell line MCF-7 and showed the accumulation of Bcl-3 in the cytoplasm of CACO-2 and HCT-116 but not in MCF-7 cells." (PMID 25929479, 2015).
colorectal cancer (23 papers, 2011 to 2025). A primary or metastatic malignant neoplasm that affects the colon or rectum. "BCL3 promoted tumour growth in mouse xenografts of colorectal cancer was directly linked to an AKT-mediated suppression of apoptosis which was dependent upon BCL3’s interaction with p50 or p52 homodimers." (PMID 38195591, 2024). "With the focus on colorectal cancer, a major cause of cancer related mortality in the UK, we describe the evidence that potentially explains why increased BCL-3 expression is associated with poor prognosis in colorectal cancer." (PMID 31930327, 2020). "It is important to remember that in the O’Carroll study, germline Bcl-3 KO will affect the immune cell compartment which will play a key role in colitis associated colorectal cancers, as discussed in the previous section." (PMID 31930327, 2020). "The proto-oncogene BCL-3 is upregulated in a subset of colorectal cancer patients and expression is associated with poorer patient outcome." (PMID 31591445, 2019). "A study by Puvvada et al22 showed an association between BCL-3 expression and clinical outcome in colorectal cancer; a strong correlation between nuclear BCL-3 expression and poor prognosis was reported." (PMID 26033966, 2016). "Additionally, in a mouse model of colitis-associated colorectal cancer whereby tumours are initiated through the addition of azoxymethane/dextran-sodium sulphate, BCL3 was shown to have a protective effect." (PMID 38195591, 2024). "Additionally, Bcl3 loss can induce apoptosis in normal mammary gland development, while Bcl3/ NF-κB activity can promote tumour survival in colorectal cancer cells through AKT activation." (PMID 38255248, 2024). "Conversely, a recent paper has suggested Bcl-3 may play a protective role in colitis-associated colorectal cancers." (PMID 31930327, 2020). "Our study helps to unravel the mechanism by which BCL-3 is linked to poor prognosis in colorectal cancer; we suggest that targeting BCL-3 activity represents an exciting therapeutic opportunity potentially increasing the sensitivity of tumour cells to conventional therapy." (PMID 26033966, 2016). "Colorectal cancer cells can develop an ‘addiction’ to Bcl3 and are therefore primed to undergo apoptosis in response to Bcl3 suppression." (PMID 38255248, 2024). "More recently the link between BCL3 and double-strand break repair was reinforced in models of colorectal cancer in which suppression of BCL3 was shown to sensitize to DNA damage-inducing chemotherapy and gamma irradiation." (PMID 38195591, 2024). "In colorectal cancer cells BCL3 promotes phosphorylation of c-Myc via ERK1/2, extending the half-life of c-Myc and reducing levels of ubiquitinated protein ensuring c-Myc prolonged presence and consequently its sustained transcriptional activity." (PMID 38195591, 2024). "In colorectal carcinoma cells overexpression of BCL3 promoted both Ser473 and Thr308 phosphorylation of AKT and downstream target FOXO1/3a and GSK3β, while siRNA knockdown of BCL3 decreased phospho-AKT and downstream targets, in response to hypoxia." (PMID 38195591, 2024). "BCL-3 overexpressed in breast cancer, nasopharyngeal carcinoma, endometrial cancer, hepatocellular carcinoma and colorectal cancer have been identified." (PMID 35488886, 2022). "It is known from colorectal cancer that BCL3 promotes WNT-signaling and enhances β-catenin signaling." (PMID 35020071, 2022). "The proto-oncogene BCL-3 is upregulated in a subset of colorectal cancers (CRC), where it has been shown to enhance tumour cell survival." (PMID 35468497, 2022). "In conclusion, we have demonstrated a novel role for BCL-3 in conferring resistance to IR in colorectal cancer cells and in mouse intestine." (PMID 35468497, 2022). "BCL-3 is a potent survival factor in colorectal cancer, and activates the pro-survival AKT/PKB pathway." (PMID 31930327, 2020).
colorectal cancer (continued). "More recent work has shown the importance of the alternative NF-κB pathway in regulation of BCL-3 transcription in colorectal cancer." (PMID 31930327, 2020). "Recently we have shown that BCL-3 is an important co-activator of β-catenin/T-cell factor-mediated transcriptional activity in colorectal cancer cells, increasing expression of Wnt-regulated intestinal stem cell genes." (PMID 31930327, 2020). "Although reported to be overexpressed in a subset of colorectal cancers (CRCs), the role of BCL-3 expression in colorectal tumorigenesis remains poorly understood." (PMID 30792270, 2019). "As BCL-3 is an established NF-κB homodimer binding protein and NF-κB1 (p105/p50) is expressed in colorectal tissue, we studied the involvement of BCL-3:NF-κB complexes in colorectal cancer cell growth in vivo." (PMID 26033966, 2016). "We have shown for the first time that BCL-3 promotes the growth of colorectal cancer cells through activation of the AKT pathway, increasing tumour cell yield both in vitro and in vivo." (PMID 26033966, 2016). "We report increased BCL-3 expression in human colorectal cancers and demonstrate that BCL-3 expression promotes tumour cell survival in vitro and tumour growth in mouse xenografts in vivo, dependent on interaction with NF-κB p50 or p52 homodimers." (PMID 26033966, 2016). "Bcl-3 localization in colorectal cancer was assessed by immunohistochemistry on tissue microarray and freshly isolated colon from patients." (PMID 25929479, 2015). "In summary, we identified a potential role of Bcl-3 in colorectal cancer through its localization in cells and tissue samples." (PMID 25929479, 2015). "Indeed, a recent study demonstrated that Bcl3-/- mice exhibit increased sensitivity to cisplatin chemotherapy in colorectal cancer, thus offering a rationale for targeting Bcl3 as an adjuvant to conventional therapies." (PMID 39123403, 2024). "The role of Bcl-3 in cancer hallmarks has been published recently for colorectal cancer." (PMID 38238702, 2024). "Expression of BCL3 and β-catenin was inversely correlated in colorectal cancer cell lines and targeted knockdown of β-catenin promoted BCL3 expression, while stimulation of the pathway by exogenous Wnt3a administration also led to an increase in BCL3 expression in the same cell lines." (PMID 38195591, 2024). "A recent study showed that Bcl-3 could enhance the Wnt signaling cascade by maintaining the acetylation of β-catenin at K 49 in colorectal cancer." (PMID 35494070, 2022). "Functionally, BCL-3 could participate in regulating the colony formation and cell cycle progression by regulating ubiquitination-mediated degradation of c-Myc in colorectal cancer." (PMID 35488886, 2022). "Various mechanisms of BCL-3-mediated tumour promotion have been observed in colorectal cancer." (PMID 31930327, 2020). "We suggest that targeting BCL-3 function (through suppressing the stem-like potential of cancer cells) would increase the tumour response to conventional treatment, reduce the chance of relapse and hence improve the prognosis for colorectal cancer patients." (PMID 31930327, 2020). "Vice versa, in colorectal cancer cells, Bcl-3 was found to activate AKT." (PMID 33228022, 2020). "The results indicate that increased BCL-3 expression seen in some colorectal cancer could aid homologous recombination allowing more efficient repair of DNA after damage, enhancing tumour survival." (PMID 31591445, 2019). "Furthermore, expression of the NF-κB co-regulators, such as BCL-3, has been shown to worsen prognosis in colorectal cancer, highlighting the importance of the whole pathway." (PMID 28641310, 2017). "Treatment with 5-ASA suppressed BCL-3 expression in colorectal cancer cells." (PMID 26033966, 2016).
colorectal cancer (continued). "Since the discovery that Bcl-3 is an oncogene involved in leukemia, we and others have determined that Bcl-3 also functions as an oncogene in solid tumours including breast, nasopharyngeal, endometrial carcinomas, colorectal cancer, and prostate cancer." (PMID 25929479, 2015). "Importantly, BCL-3 has been shown to play multiple roles in the promotion of colorectal cancer." (PMID 31930327, 2020). "Similar genomic landscapes and active Bcl3 transcription were also observed in other cancer cell lines, including lung adenocarcinoma (A549), lymphoblastoid (GM12878), and colorectal carcinoma (HCT-116), suggesting a shared regulatory mechanism governing Bcl3 expression across diverse cancer types." (PMID 40884402, 2025). "BCL-3 was demonstrated to bind to β-catenin; RNAi-mediated BCL-3 suppression reduced β-catenin/T-cell factor-dependent transcription and the expression of intestinal stem cell genes and Wnt targets LGR5 and ASCL2, both widely accepted colorectal cancer stem cell markers." (PMID 31930327, 2020).